STAT1 (signal transducer and activator of transcription 1)
Diseases named in the same sentence as STAT1 in open-access papers (continued):
Sharing a sentence is not in itself a finding about the gene and the disease.
tumor (continued). "Previous research from our group has identified an antitumor role for the murine ortholog caspase-11 during tumor initiation, showing that Casp-11−/− mice have defective STAT1 activity, rendering them highly susceptible to the AOM-DSS model of colitis-associated cancer." (PMID 39866724, 2025). "Notably, we observed a marked reduction in STAT1 expression levels within NK cells, suggesting that bafilomycin disrupts the mechanisms underlying NK cell-mediated tumor surveillance." (PMID 40650051, 2025). "In the present study, STAT1 was found to be associated with patient prognosis and tumor immunity." (PMID 40226609, 2025). "In the mice tumor model, we observed that the deficiency of STAT1 or IFITM3 alone could induce fragile TI-Treg cells and thus strengthen anti-tumor immunity." (PMID 38167862, 2024). "This study suggests that suppressing IL-17A could potentially decrease tumor progression associated with STAT1 deficiency." (PMID 39411241, 2024). "Signal transducer and activator of transcription 1 (STAT1) has been linked to anti-tumor immune responses, and H. pylori might be involved in the regulation of its expression." (PMID 39228892, 2024). "Moreover, they provide evidence that its tumor suppressive function is linked to repression of the STAT1-mediated IFN response." (PMID 38806478, 2024). "Additionally, the association of Rap1A and Krit1 in cytoskeletal regulation and the presence of STAT1, linked to the urea cycle and tumor development, offered insights into Lucena 1’s distinctive biology." (PMID 39272999, 2024). "By contrast, CD11b+ cells expressing STAT1 phosphorylated at Tyr701 (pSTAT1), which is the hallmark transcription factor of inflammatory M1 macrophages, were increased, likely also contributing to the tumor-killing effects." (PMID 38789520, 2024). "On the other hand, ESCO2 was shown to regulate mTOR in tumor cells; therefore, STAT1 may also be associated with ESCO2’s molecular activity." (PMID 37968576, 2023). "Combined with the information on drug responsiveness from The Cancer Therapeutics Response Portal database and information on gene expression profiles of tumor cell lines, we found that twenty of thirty drugs’ sensitivities were shown to be positively linked to STAT1." (PMID 37646041, 2023). "Chronic-IFN-γ-treatment of tumour cells induced STAT1-associated epigenomic changes, promoting IFN-γ-independent expression of ISGs including ligands for multiple TCIRs, such as TNF receptor superfamily member 14 (TNFRSF-14) and MHC-II, that conferred resistance to ICBT in preclinical models." (PMID 37503572, 2023). "We employed two experimental models of HNSCC to better characterize the specific immunological responses associated with T cell stimulation using the IR HNSCC tumor antigen: (i) LY2 HNSCC cells injected into STAT1-deficient BALB/c mice and (ii) MOC2 HNSCC cells injected into wild-type C57BL/6 mice." (PMID 37444444, 2023). "Among them, HLA-B and STAT1 are well-known proteins associated with anti-tumor immunity." (PMID 37380972, 2023). "Importantly, loss of the tumor suppressors STAT1 and SOCS1 appoint to loss of inhibitory functions and loss of negative feedback control." (PMID 36341492, 2022). "Therefore, targeting STAT3 can inadvertently lead to the downregulation of STAT1 and the associated advantages to tumor cells." (PMID 35053592, 2022). "Alternatively, MDSC populations have been shown to expand in response to chronic inflammation, and their deficiency may be due to the failure of Stat1−/− mice to initiate a robust anti-tumour response during the early stages of head and neck carcinogenesis." (PMID 35595823, 2022). "By binding this site, STAT1 can promote NAMPT expression in tumor-associated macrophages." (PMID 35515130, 2022). "To determine whether global STAT1 deficiency affects proliferation and apoptosis of tumour cells in vivo, we measured Ki-67 and caspase 3 expression in tumours by RT-qPCR and immunohistochemistry." (PMID 35595823, 2022).
tumor (continued). "Furthermore, new studies show that down-regulated STAT1 expression in peripheral blood of GC patients results in immune escape from gastric epithelial cancer caused by decreased anti-tumor immune function." (PMID 36311733, 2022). "Transcription factor (TF) activity prediction, using the DoRothEA resource, to identify potential regulons responsible for the signalling and phenotypes associated with HPS in HiFi tumours revealed a strong association with STAT1, STAT2, IFN (IRF1, IRF9) and NFκB (NFKB1, REL, RELA, RELB) TFs." (PMID 35477539, 2022). "We asked what role, if any, these cells may have in tumor development associated with STAT1 deficiency." (PMID 34299314, 2021). "The tumor-suppressing role of STAT1 is probably associated with its function in the immune system." (PMID 34572789, 2021). "A more convincing evidence is that STAT1 knockout mice are highly susceptible to some tumours." (PMID 34544433, 2021). "To analyze whether IL-17 may promote tumor growth via STAT3 during STAT1 deficiency, we evaluated STAT3 phosphorylation (pSTAT3) in colon tissue." (PMID 34299314, 2021). "To evaluate if IL-17 was involved in this observed accumulation of CD11b+Ly6ClowLy6G+ cells and the increased rate of tumor development resulting from STAT1 deficiency, we examined the impact of anti-IL-17 treatment on MDSCs and neutrophil recruitment during CAC progression." (PMID 34299314, 2021). "Indeed, we demonstrated that the homing and efficacy of PTPN2‐deficient CAR T cells was reliant on tumours expressing STAT‐1‐driven CXCR3 chemokines." (PMID 31803974, 2020). "Moreover, PD-L1 expression is regulated by IFN-γ-mediated STAT1 activation and is upregulated by miR-21 depletion and the consequent STAT1 activation in cultured bone marrow-derived macrophages and in tumor-associated macrophages (TAM) residing in tumors." (PMID 32192047, 2020). "STAT1 plays an important role in growth arrest and promoting apoptosis, and is implicated as a tumor suppressor; while STAT3 suppresses apoptosis and promotes tumor cell proliferation, and plays a critical role in the invasion and metastasis of malignant tumors." (PMID 33361763, 2020). "Future work will need to test whether there exists an association between STAT1, tumor budding, and outcome." (PMID 32275681, 2020). "Furthermore, an increasing amount of studies have indicated that STAT1 is associated with radio- and chemoresistance in multiple tumor entities." (PMID 31803233, 2019). "Thirdly, our observations that BRCA1-mutated cells are resistant to IFN-γ-mediated cytotoxicity and to STAT1 downregulation could have implications for understanding responses to anti-tumor immunity in BRCA1-mutated cancers." (PMID 31840082, 2019). "The reason for these two opposite functions of IFN/STAT1 pathway remains elusive but it might be due to the difference of tumor types and genetic background, such as mutations of apoptosis- and cell cycle-related genes." (PMID 30709063, 2019). "Similarly, the high tumor cell STAT1 has been linked to the recruitment of CD33+ myeloid cells to the TME, with increased infiltration correlating with progression from ductal carcinoma in situ to invasive carcinoma in women and murine models." (PMID 31842362, 2019). "Our findings suggest that STAT1 plays a role as a tumor suppressor molecule in inflammation-associated carcinogenesis, particularly during the very early stages of CAC initiation, modulating immune responses as well as controlling mechanisms such as apoptosis and cell proliferation." (PMID 30235866, 2018). "Indeed, STAT1-deficient tumor cells were more susceptible to NK cells while STAT1-proficient tumor cells were more sensitive to CD8+ T cells." (PMID 29780381, 2018). "Although STAT1 activation is required to trigger anti-tumor immune responses, and therefore STAT1 deficiency may prevent the induction of anti-tumor immunity, persistent STAT1 activation may be associated with therapeutic resistance, as in the case of RT." (PMID 30186768, 2018).
tumor (continued). "Given the abundance of macrophages in the tumor-associated stroma, we reasoned that Stat1-null tumors might secrete macrophage chemoattractants." (PMID 28865492, 2017). "This elevated STAT1 response may render tumours susceptible to the re-establishment of immune evasion following selective STAT3 re-activation." (PMID 28276425, 2017). "Comparing the proteomic profiles of vSCC morphologic variants indicates that increased expression of collagen subunits and decreased expression of STAT1 are associated with a more aggressive tumor variant, defined by increased incidence of nodal metastases and tumor recurrence." (PMID 29225558, 2017). "However, MT/Shc2F/2F tumours that express low (5372) or high (5376) STAT1 levels are similarly susceptible to immune surveillance." (PMID 28276425, 2017). "The hallmark of HNSCC tumour cells is an imbalance in STAT1/STAT3 signalling." (PMID 28315228, 2017). "Comparing the proteomic profiles of vSCC variants indicates that higher expression of collagen subunits and lower expression of STAT1 are associated with a more aggressive vSCC variant that is characterized by an infiltrative tumor morphology and a fibromyxoid stromal response." (PMID 29225558, 2017). "Interestingly, expression of the macrophage marker CD68 was specifically associated with tumor epithelium-specific STAT1 expression." (PMID 24725474, 2014). "The present study further suggests that the combined targeted inhibition of STAT1, ARTD8, ARTD9 and/or DTX3L could increase the efficacy of chemotherapy or radiation treatment in prostate and other high-risk tumor types with an increased STAT1 signaling." (PMID 24886089, 2014). "For instance, loss of tumor suppressor genes such as Bin-1 in tumors drives IDO induction via STAT1 and nuclear factor kB, two signaling molecules that have been identified to be key for the inducible IDO expression in myeloid and mesenchymal cells via IFN-g and toll-like receptor (TLR) ligands." (PMID 24657910, 2014). "STAT1 is one of the pathways in MDSCs activation; Gabrilovich demonstrated that STAT1 activation in tumor-associated macrophages is responsible for the upregulation of inducible nitric oxide synthase (iNOS) and arginase 1 activity in these cells, which results in T-cell suppression." (PMID 23307253, 2013). "Also, because tumors from carcinogen-treated wild-type animals grow more rapidly when transplanted into the Stat1-deficient animals than they do in a wild-type host, Stat1 contributes to tumor immunity." (PMID 19274102, 2009). "Here we hypothesized that stable KD of STAT1 in SCC61 would also suppress tumour growth and cause radio sensitization of SCC61." (PMID 19891767, 2009). "Based on these findings, we hypothesized that in vivo selection of developing tumor clones would be associated with the ability of tumor cells to overexpress the IFN/STAT1 pathway while resisting IFNγ-mediated cytotoxicity." (PMID 19503789, 2009). "However, the majority of genes and proteins associated with STAT1 were involved in regulation of glycolysis, a pathway essential to proliferating tumour cells." (PMID 19891767, 2009). "However, STAT1 KD tumours showed significantly decreased expression of GG, CC and OP genes and proteins relative to WT tumours, indicating that STAT1 is associated with protecting GG, CC and OP expression following IR." (PMID 19891767, 2009). "Our results identify a previously uncharacterized function of STAT1 in tumours: expressional regulation of genes encoding proteins involved in glycolysis, the citrate cycle and mitochondrial oxidative phosphorylation, with predominant regulation of glycolytic genes." (PMID 19891767, 2009). "Consistent with our observations are recent reports indicating that constitutive overexpression of STAT1 and STAT1-dependent genes is associated with protection of tumor cells from genotoxic stress following treatment with fludarabine, doxorubicin (Dox), cisplatin, and the combination of IR and Dox." (PMID 19503789, 2009).
tumor (continued). "Recently, we reported that constitutive overexpression of the STAT1 pathway is associated with suppression of caspases 8, 9, and 3 and therefore with suppression of the apoptotic response in radiation and interferon resistant tumor cells." (PMID 19503789, 2009). "The anti-tumor properties of Stat1 have mainly been linked to its function downstream of IFNs." (PMID 18941537, 2008). "However, STAT1’s role in cancer biology as well as the mechanism underlying its tumor-suppressive or oncogenic properties remain unclear." (PMID 40407590, 2025). "Therefore, anti-miR-21 therapy might not only act on tumor cells but also re-polarize tumor-associated macrophages towards an anti-tumor (M1) phenotype by preventing miR-21’s suppression of STAT1/NF-κB signaling in those immune cells." (PMID 41007803, 2025). "Notably, STAT1 is often considered a tumor suppressor because STAT1-deficient mice have been shown to be more prone to spontaneous and chemically induced tumor formation than wild-type mice, so there is an urgent need to find specific target inhibitors of STAT3." (PMID 37173892, 2023). "Several reports have observed that the deletion or inactivation of STAT1 could destroy the IFN signal transduction, and STAT1 expression is associated with better prognosis, suggesting that the anti-tumor immunity of IFN may be achieved through the JAK/STAT pathway." (PMID 36612165, 2022). "We have demonstrated that IL-17 neutralization during the early stages of tumor transformation results in the reduced recruitment of neutrophils, reduced CD11b+Ly6ClowLy6G+ cell populations, and lower iNOS expression in the intestine during STAT1 deficiency, which results in reduced tumorigenicity." (PMID 34299314, 2021). "Our study reveals that the effect of host STAT1 deficiency on tumor development can be reversed upon IL-17-blockade treatment, which correlates with a decreased accumulation of CD11b+ Ly6ClowLy6G+ cells and neutrophils and a remarkable reduction in tumor growth." (PMID 34299314, 2021). "The selection pressure to down-regulate or lose STAT1 in tumor cells may have more than one cause as the loss of STAT1 has several important consequences: the tumor cells lose responsiveness towards interferon-mediated growth inhibition (interferons are important players in tumor surveillance)." (PMID 22185785, 2011). "We hypothesised that the development of resistance to the constitutively expressed Stat1 pathway in tumour cells is associated with suppression of the Stat1-dependent apoptotic pathways or/and clonal selection of the cells resistant to Stat1-dependent apoptosis." (PMID 19437244, 2009). "IRF1, IRF9 and STAT1 in lymphoid cells of C1 participated in anti-tumor immune response by impacting target genes CD8A, HLA-A/E, TAP1 and PD-1." (PMID 42074110, 2026). "PTPN2 inhibition (PTPN2i) increases HNSCC tumor cell STING by restoring IFNγ-STAT1-mediated induction of STING mRNA." (PMID 42069723, 2026). "The identification of a previously unrecognized APC/PTPN13/STAT1-dependent tumor immune-suppressive mechanism in this study represents a significant advance, offering a compelling strategy for development of therapeutic interventions for CRC." (PMID 41486293, 2026). "Together, these results propose that stromal WISP-1 acts as a paracrine inducer of STAT1 activity in TAMs, thereby reshaping macrophage polarization toward an anti-tumor state." (PMID 41522359, 2026). "Immunofluorescent analysis of primary tumor tissues revealed a marked increase in phosphorylated STAT1 in M2 TAMs (pSTAT1+/CD206+) following injection of ApoSQ-CAF CM." (PMID 41522359, 2026). "Functional assays indicate that IFNγ contributes to CTL-mediated tumor cell death by acting in concert with granzyme B and perforin to increase cytotoxicity and promote apoptosis via the IFNγ-STAT1-caspase-3 pathway." (PMID 41781697, 2026).
tumor (continued). "Elevated STAT1 expression in macrophages correlates with improved patient survival and a more active tumor immune landscape, suggesting its potential as a predictive biomarker for immunotherapy responsiveness." (PMID 41522359, 2026). "While STAT3/STAT5 are established oncogenes and STAT1/STAT2 are classically viewed as tumor suppressors, emerging evidence indicates context-dependent roles in tumorigenesis." (PMID 42195004, 2026). "Single-cell analysis demonstrated tumor-cell-autonomous upregulation of STAT1 and STAT2 in the HNSCC dataset." (PMID 42195004, 2026). "This is because the APC11 peptide mimics the effect of APC overexpression, which can further enhance the inhibition of PTPN13 and the activation of IFNγ-STAT1 signaling in APC intact tumor cells, thereby enhancing the immune response." (PMID 41486293, 2026). "The CD3- and CD20-negative splenic tumor cells exhibited immunopositivity for both tyrosine-phosphorylated STAT1 and tyrosine-phosphorylated STAT3." (PMID 40287766, 2025). "This metabolic switch not only facilitates tumor growth but also cooperates with the STAT1-PD-L1 axis to enhance immune evasion." (PMID 41359111, 2025). "Our results further refine the emerging view of STAT1 as a context-dependent mediator of tumor progression." (PMID 41511309, 2025). "Our analysis revealed that interferon response in the blood was positively associated with positive response predictors such as tumor chemokine signaling, T and B cell scores, STAT1 signaling, and tumor interferon scores." (PMID 40671797, 2025). "SECTM1 is upregulated by IFN-γ (interferon-gamma)/STAT1 (signal transducer and activator of transcription 1) signaling in immuno-hot tumors, further highlighting its role in tumor-immune interactions." (PMID 40362379, 2025). "Tumor cells utilize the TRIM65–JAK1/STAT1 axis to suppress M1‐like polarization of macrophages and promote tumor growth." (PMID 40717900, 2025). "Our analysis found that ETS1 is co-expressed with STAT1 in immunosuppressive tumor subpopulations and promotes the upregulation of immune checkpoint ligands and T cell exhaustion markers." (PMID 40948762, 2025). "As an interferon-driven transcription factor, STAT1 is known for its anti-microbial functions and typically acts as a tumor suppressor by inducing apoptosis and inhibiting cell proliferation at both transcriptional and non-transcriptional levels." (PMID 40287766, 2025). "The in vivo experiment showed that tumor weight and volume were obviously reduced in the sh‐STAT1‐1 or sh‐STAT1‐2 groups compared to the sh‐NC group." (PMID 40387572, 2025). "CXCL11, a protective biomarker, promotes M1 macrophage polarization via JAK2/STAT1, supporting the anti-tumor role of M1 TAMs in OC." (PMID 41280929, 2025). "The STAT1-IFNγ regulatory axis has been reported to enhance anti-tumor immunity by recruiting CXCR3+CD8+ T cells and CXCR3+ NK cells." (PMID 40346580, 2025). "We propose that tumor-derived lactate orchestrates malignant behaviors through the “H3K18la-STAT1-LDHA” regulatory axis." (PMID 41208879, 2025). "Specifically, IFN-γ activates the JAK/STAT1/interferon regulatory factor 1 (IRF1) signaling pathway to upregulate ACSL4 transcription in tumor cells by promoting IRF1 binding to ACSL4 promoter region IFN-stimulated response elements." (PMID 40169575, 2025). "Combining poly I:C with R838 treatments has led to tumor regression, marked by increased macrophage infiltration with a high M1 to M2 ratio, primarily through the activation of the STAT1 pathway." (PMID 39843434, 2025). "Our findings collectively demonstrate a positive feedback mechanism wherein tumor-derived lactate promotes H3K18la-mediated STAT1 transcription, which enhances LDHA expression and lactate production." (PMID 41208879, 2025).